BLM (BLM RecQ like helicase)
Diseases named in the same sentence as BLM in open-access papers (continued):
Sharing a sentence is not in itself a finding about the gene and the disease.
cancer (continued). "Heterozygous carriers of BLM variants have not been extensively studied but there are a few studies showing mixed results with regard to cancer risk." (PMID 35782872, 2022). "However, till recently only the small molecule ML216 had been developed to target BLM, which is still poorly characterized in treating cancer cells." (PMID 36569948, 2022). "In brief, BLM is considered a potential and promising target for cancer treatment." (PMID 36499126, 2022). "In addition to BLM and WRN, mutations in DDX3X have been associated with several diseases, specifically several cancers, epilepsy, and female intellectual disability." (PMID 35626643, 2022). "Based on known cancer predisposing genes curated from COSMIC database and other pan-cancer germline genomic studies, we found a total of 6 damaging or potentially damaging heterozygous germline variants including missense mutation of BLM and FANCI." (PMID 35860547, 2022). "As the genomic instability induced by BLM loss in the germ line has a high impact on carcinogenesis, reduced somatic levels in PBL from healthy aged women very likely contribute to the increasing incidence of cancer with age." (PMID 34506302, 2021). "To complement EA/ET analyses, we created a genome-wide mutability map that reveals low mutability in conserved ancient genes such as BLM that are often overexpressed in cancer cells leading towards reverse evolution from the multicellular back to a primordial unicellular hyperproliferative state." (PMID 34966786, 2021). "Taking this evidence into consideration, it can be argued that in contrast to tumor suppressor, BLM may be involved in promoting cancer development." (PMID 33777104, 2021). "It is possible that miRNA-mediated BLM turnover can be altered in specific types of cancers." (PMID 33777104, 2021). "Furthermore, BLM-deficient cells increase genetic exchanges between homologous chromosomes, resulting in loss of heterozygosity (LOH), which typically increases in cancer and aging cells." (PMID 34966786, 2021). "However, recent evidence shows BLM mRNA to be overexpressed in a plethora of cancers including colon, breast, and hematological cancers when compared with the normal samples." (PMID 33777104, 2021). "Furthermore, an in silico examination of the TCGA datasets revealed that BLM mRNA is overexpressed in all types of cancer tissues as compared with normal tissues." (PMID 33777104, 2021). "We propose to rationalize and integrate the dual functions of BLM both as a tumor suppressor and maybe as a proto-oncogene, and enlist the plausible mechanisms of its deregulation in cancers." (PMID 33777104, 2021). "Whether these interactions also have an effect on the BLM function in cancer needs to be explored further." (PMID 33777104, 2021). "A number of experimental and computational studies have implicated RECQ helicases – primarily BLM and WRN - as potential targets for cancer therapy, due to the synthetic lethality of their silencing or downregulation with genetic defects inherent in a range of different cancers." (PMID 33647232, 2021). "Interestingly, recent studies have also demonstrated that BLM is highly expressed in multiple cancer tissues and even acts as a novel cancer biomarker." (PMID 33828983, 2021). "Exploration studies on these lines will allow a better understanding of the rewiring of BLM, and its Janus-like character may have important implications in the study of neoplastic transformation and cancer development." (PMID 33777104, 2021). "In addition to this, there has been a growing interest in elucidating the importance of epigenetic regulators in BLM expression in cancers." (PMID 33777104, 2021). "BLM homozygous null BLMm3/m3 mice are viable, fertile, and more cancer prone with and without tumor predisposing factors like gamma irradiation." (PMID 33777104, 2021).
cancer (continued). "Moreover, several other compounds targeting proteins involved in DNA repair mechanisms have already shown promising results as potential new anti-cancer drugs in pre-clinical studies, such as BLM, WRN, RAD52, or MRE11 inhibitors." (PMID 33036275, 2020). "Given the close relationship between the WRN and BLM helicases, and the fact that the silencing of both is used in the treatment of multiple forms of cancer, it stands to reason that certain shared pathways govern the link between these two proteins and cancer cell proliferation." (PMID 31210839, 2019). "There were 63 cancers in 75 families with a BLM mutation (84%) versus 11,511 cancers in 13,556 BLM mutation negative families (85%)." (PMID 31614901, 2019). "BRCA2, BLM, ERCC2, RECQL, REV3L and RIF1 were among the most promising candidates, with some of them previously associated with predisposition syndromes to other cancers." (PMID 30871259, 2019). "In none of these separate evaluations was there evidence of cancer predisposition for carriers of a BLM pathogenic mutation." (PMID 31614901, 2019). "We also asked if cancers with and without BLM mutations showed differences in their clinical presentation and survival." (PMID 31614901, 2019). "Bloom syndrome, RecQ helicase protein (BLM), is required to maintain the intra-S-phase checkpoint, and its deregulation may be important for cancer progression (54, –, 57)." (PMID 25477524, 2015). "Because accelerated cell division imposed by activated MYC is associated with increased risk of replication errors and DNA damage, it is reasonable to postulate that cancer cells with activated MYC are particularly sensitive to reduced RecQ helicases such as BLM and WRN (59, –, 62)." (PMID 25477524, 2015). "Furthermore, somatic mutations of SOD1 are rare in cancer, and those few that do occur are mutually exclusive of those occurring for RAD54B, BLM and CHEK2." (PMID 26318585, 2015). "Besides their biological importance in the prevention of tumorigenesis and accelerated aging, WRN and BLM are also new targets for cancer chemotherapy." (PMID 25400656, 2014). "This indicates that BLM is possibly involved at an early stage during neoplastic transformation - a step that maybe common for all forms of cancer." (PMID 21050475, 2010). "Mutations in three of these helicase genes, RECQ2 (BLM), RECQ3 (WRN) and RECQL4, result in the rare autosomal recessive disorders of Bloom, Werner and RTS, which share the general characteristics of genomic instability and cancer predisposition." (PMID 20113479, 2010). "Moreover, we also uncover that loss of EXD2 is synthetic sick with BLM, DNA2 and POLD3, which could represent an attractive therapeutic target against ALT-dependent cancers." (PMID 37105990, 2023). "Finally, heterozygous deleterious germline mutation BLM and FANCI were identified which could predispose the patient to higher cancer risk." (PMID 35860547, 2022). "A recent report utilizing the computation approach has also identified that BLM overexpression was related to poor overall survival (OS) in lung and gastric cancer patients and thus may act as a critical prognostic marker for the detection of these cancers." (PMID 33777104, 2021). "BLM unwinds specific DNA structures including D-loops, forked duplexes, G-quadruplex (G4) DNA and Holliday junctions through its 3′-to-5′ DNA helicase activity and plays pivotal roles in multiple repair pathways that maintain genome stability and prevent cancer." (PMID 34606619, 2021). "Defects of WRN, BLM and RECQL4 may increase cancer predisposition in humans." (PMID 31897211, 2020). "Therefore, a deep understanding of how SNPs affect BLM transcription regulation and expression in cancer might be highly useful for the diagnosis and prognosis of disease." (PMID 32704157, 2020).
cancer (continued). "Mutations in BLM, WRN, and RECQ4 cause Bloom, Werner, and Rothmund–Thompson syndromes, respectively, which are associated with profound developmental abnormalities and increased cancer risk, and the latter two syndromes are also characterized by premature ageing." (PMID 30916344, 2019). "BLM, WRN, and RTS syndromes are recessive genetic disorders of humans caused by loss of function by BLM, WRN, and RTS helicases, respectively, and are characterized by genomic instability in patient cells, predisposition to various cancers and accelerated onset of aging phenotypes." (PMID 25620975, 2014). "We began with the human RecQ DNA helicase BLM implicated in the hereditary chromosomal instability disorder Bloom Syndrome, and also the human RECQ1 DNA helicase which is not yet reported to be genetically linked to a human disease but thought to play a role in cancer suppression." (PMID 25409515, 2014). "Thus, BLM plays a crucial role in preventing genetic instability and cancer." (PMID 22563370, 2012). "Thus, genetic variants of BLM and proteins that form complexes with BLM, such as TOP3A and RMI1, might affect cancer risk as well." (PMID 19432957, 2009). "Still, it should be noted that apart from factors as age and sex, we have not evaluated cancer-specific risk factors, which could influence the associations between SNPs in the BLM complex and cancer risk." (PMID 19432957, 2009). "We subsequently knocked out endogenous BLM in EPI-resistant cancer cells (E-resistant-BKO) and then rescued them with WT, K24R, K31R, or K38R BLM." (PMID 40634292, 2025). "While we identify MRP2 to be regulated by the RAD54-BLM interaction, identification of other genes that are coregulated by both BLM and RAD54 will also better understanding of the cancer resistance." (PMID 38421735, 2024). "BLM, WRN, RECQL4, and RECQL5 were repressed by stromal and/or immune elements in most types of cancer, while RECQL exhibited reverse patterns." (PMID 37626815, 2023). "Conversely, BLM, RECQL4, and RECQL5 displayed diverse correlations with stem cell scores across different types of cancers." (PMID 37626815, 2023). "A group of new BLM inhibitors known as isaindigotone derivatives were shown to interfere with BLM/DNA interactions and control HRR by encouraging the accumulation of Rad51 in cancer cells." (PMID 36499126, 2022). "BLM is a DNA helicase that performs important roles in DDR pathways and is considered an attractive target for cancer therapy." (PMID 36499126, 2022). "BLM is a DNA helicase with significant functions in DDR pathways and is viewed as a promising target for cancer treatment." (PMID 36557923, 2022). "Other human helicases, such as BLM and WRN, are also upregulated in multiple tumors, driving cancer cells to rapidly proliferate, supporting oncogenic activation and potentially playing distinct functions in driving DNA replication stress." (PMID 34381789, 2021). "Furthermore, previous studies have supposed that BLM serves as a cancer suppressor through targeting the proto-oncogene c-MYC, and recent researches also proposed that a series of malignancies are associated with the overexpression of the MYC gene and loss of BLM function." (PMID 33828983, 2021). "The experiment results indicated that cancer cells (QBC939 and RBE) expressed higher levels of BLM than normal cells (HiBEC) at both the mRNA and protein levels." (PMID 33828983, 2021). "Of note, BLM and FANCD2 were differentially expressed between the Long TL and Short TL groups in 30% (9/30) of cancer types." (PMID 32784588, 2020). "Future studies, possibly utilizing conditional knockout cells for FANCM and BLM, should refine this intriguing cellular scenario and open the way to novel avenues for curing ALT cancers." (PMID 31138795, 2019).
cancer (continued). "Of those tested in cell-based assays, small molecule inhibitors of DNA unwinding catalyzed by WRN, BLM, and DNA2 all negatively affect proliferation of cancer cells and induce DNA damage and/or chromosomal instability." (PMID 29998112, 2018). "Accordingly, this study identifies two evolutionarily conserved SL interactions, namely BLM SOD1 and CHEK2 SOD1, and defines SOD1 as a novel candidate drug target in cancers harboring BLM and CHEK2 defects." (PMID 26318585, 2015). "Collectively, these data identify SOD1 as a novel candidate drug target in BLM and CHEK2 cancer contexts, and further suggest that 2ME2, ATTM and LCS-1 are lead therapeutic compounds warranting further pre-clinical study." (PMID 26318585, 2015). "Patients of BLM and a subset of patients with RTS who lack functional BLM and RTS helicases, respectively, manifest clinical phenotypes of genomic instability and a high incidence of cancers." (PMID 25620975, 2014). "Ten patients had germline mutations affecting cancer predisposition genes not typically linked to WT: CHEK2 in 4 children, and BLM, BRCA2, CDKN2A, FMN2, PIK3C3, and STK11 in one patient each." (PMID 40340749, 2025). "Interestingly, Metascape for the first time demonstrated a physical interconnection between CALML3 and DNA repair proteins (BRCA2—Breast Cancer Gene 2, BLM—Bloom syndrome protein, SLX4—Structure-Specific Endonuclease Subunit)." (PMID 41465209, 2025). "This review will discuss the BLM functions in ALT, including processing recombination intermediates during BIR or enhancing DSB end resection, and explores emerging therapeutic strategies targeting ALT-positive cancers." (PMID 40025590, 2025). "Finally, we show that co-depletion of EXD2 with BLM, DNA2 or POLD3 confers synthetic lethality in ALT cells, identifying EXD2 as a potential druggable target for ALT-reliant cancers." (PMID 37105990, 2023). "To further establish whether the interplay between SETX and POLD3/BLM impacts genome stability, we examined genomic signatures in cancer databases with relation to SETX, POLD3 and BLM expression." (PMID 35440629, 2022). "It is noteworthy that our study was the first time that identified BLM, WRN, XPA, and RAD54L germline P/LP alterations in BTC patients, supporting consideration of expanded genetic testing for those with positive family cancer history or early-onset disease (below 45 years old)." (PMID 36072793, 2022). "ML216 has been used to characterize BLM function in HR, but its potential as an anti-cancer therapy has barely been addressed and to date no available studies have evaluated it in the context of MM." (PMID 36569948, 2022). "We also found upregulation of ancient genes including BLM, which supports a non-random and concerted cancer process: reversion to a unicellular, proliferation-uncontrolled, status by breaking multicellular constraints on cell division." (PMID 34966786, 2021). "To further investigate the potential role of the USP37–BLM axis as a target for cancer therapy, we knocked down USP37 or BLM individually or together in MCF7 cells or MDA-MB-231 cells with high USP37 level, and examined the cell survival following cisplatin or IR treatment." (PMID 34606619, 2021). "As a cancer target, the function of RNF4 in turnover of sumoylated BLM and other HR proteins could perhaps be utilized to slow recovery in replication stressed cells." (PMID 34868226, 2021). "The 12.2% de novo germline mutation rate in MMR genes and other non-CRC cancer susceptibility genes (BRCA1, BLM, and NTHL1) reported herein for the young sporadic CRC group is reasonable and expectable." (PMID 33260537, 2020). "WRN and BLM also appear to be involved in the alternative lengthening of telomeres (ALT) pathway, that is a telomerase independent pathway, that uses HR to lengthen telomeres and is frequently activated in cancer." (PMID 33095241, 2020).
cancer (continued). "Finally, analysis of ALT cancer cells strongly suggests that MRN and BLM complex are both required for telomere recombination in these cells." (PMID 26492073, 2015). "Elevated expression of the DNA helicase genes BLM, PIF1, and RECQL4 which is generally observed in cancers may explain a recovery function from chromatin instability in ST2." (PMID 25460179, 2014). "The fact that RecQ helicases, such as BLM and RECQ1, are upregulated in tumors and provide growth advantage to cancer cells might appear incompatible with the proposed tumor suppression function of these proteins." (PMID 21752281, 2011). "Given the genetic linkage of other human RecQ helicases (WRN, BLM, RECQ4) to diseases characterized by premature aging, cancer, and chromosomal instability, we investigated the significance of human RECQ1 for genome integrity, and more specifically its role in the DNA damage response." (PMID 18074021, 2007). "Collectively, our findings reveal a novel epigenetic mechanism of BLM gene upregulation mediated by BLM-G4-STAT1 interaction and suggest that the combination therapy of G4 stabilizers with poly(ADP) ribose polymerase (PARP) inhibitors is a promising strategy for treating complex cancers." (PMID 42087785, 2026). "Moreover, we revealed that high expression of AARS1 promoted RAD51 chromatin accumulation and decreased γH2AX expression in E-resistant cancer cells overexpressing BLM-WT rather than the K24R mutant." (PMID 40634292, 2025). "While simply defining BLM as a “tumor suppressor” may not truly reflect its actual role in normal and cancer cells." (PMID 40728512, 2025). "With the formation of these many cancers, it has been noted that there is an increase in copy number, transcript, and protein levels which along with the fact there is a lack of wild-type BLM has increased the sensitivity of chemotherapeutic agents and has been labeled as pro-oncogenic." (PMID 37796556, 2023). "However, the status of these PTMs as well as their effect on BLM turnover in the context of cancer progression has not yet been examined." (PMID 33777104, 2021). "Additionally, three unsolicited variants in ATR, BLM (in two individuals), and FANCB genes presented potential cancer susceptibility, were not reported to patients." (PMID 31937788, 2020). "We conclude that the BLM gene should not be included in cancer test panels for clinical use." (PMID 31614901, 2019). "In addition, a number of non-rare variants in genes relevant to cancer risk (e.g. in BRCA1, PALB2, BLM, and others) were detected in a significant number of individuals." (PMID 26485759, 2015). "The two patients who did not meet the Jongmans’ criteria carried monoallelic PSVs in BLM and NBN, genes associated with autosomal recessive cancer predisposition syndromes, and a single heterozygous variant is generally insufficient to confer a clinically meaningful cancer risk." (PMID 40779059, 2025). "Functional autosomal recessive loss of three members of the family BLM, WRN and RECQL4, results in hereditary human syndromes characterized by cancer predisposition and premature aging, but despite the finding that RECQL5 deficient mice are cancer prone, no such link has been made to human RECQL5." (PMID 27764811, 2016). "Hence regulation of repair pathways by BLM (essentially HR) may not be the only reason for the wide spectrum cancer phenotype observed in BS patience." (PMID 21050475, 2010). "Expression levels of BLM showed higher levels in CCA tissues compared with paracancerous samples (staining index: non-cancer = 3.78 ± 0.49; cancer = 6.78 ± 0.29)." (PMID 33828983, 2021).
cancer (continued). "We observed that AND-1-binding by these cancer-related FANCJ mutants is severely compromised, while the DNA helicase activity and the interaction with other known protein binding partners (BRCA1, BLM and MLH1; see Fig. EV4A) is not altered, as compared to the wild-type protein." (PMID 38177925, 2024).